RNA5-8SN2 (RNA, 5.8S ribosomal N2)
Synonyms: RNA5-8N2
Gene: Ribosomal RNA gene on chromosome 21 (8,212,572 to 8,212,724, forward strand). Ensembl gene ENSG00000278233.
Gene Ontology:
Molecular function: structural constituent of ribosome
Cellular component: ribosome
Homologues: Orthologues: chimpanzee 5_8S_rRNA (100% identical), macaque 5_8S_rRNA (100% identical), rabbit 5_8S_rRNA (100% identical), rat 5_8S_rRNA (100% identical). Paralogues in human: 5_8S_rRNA (100% identical), RNA5-8SN1 (100% identical), RNA5-8SN3 (100% identical), RNA5-8SN4 (100% identical), RNA5-8SN5 (100% identical), 5_8S_rRNA (90% identical), 5_8S_rRNA (87% identical), 5_8S_rRNA (86% identical).